CRY2 (cryptochrome circadian regulator 2)
Diseases named in the same sentence as CRY2 in open-access papers (continued):
Sharing a sentence is not in itself a finding about the gene and the disease.
breast carcinoma (continued). "Variants of some circadian genes, such as neuronal PAS domain protein 2 (NPAS2), circadian locomotor output cycles kaput (CLOCK), cryptochrome circadian clock 2 (CRY2), and timeless circadian clock (TIMELESS), have been reported to be associated with breast cancer risk." (PMID 26253128, 2015). "Therefore, it is worth investigating whether the Cry2 acetylation status affects the progression of breast cancer by altering the circadian rhythm of breast cancer cells." (PMID 37024472, 2023). "Cry2 knockdown reportedly increased the expression of several genes involved in cell proliferation; therefore, we hypothesized that Cry2 and its reversible acetylation are involved in regulating breast cancer cell proliferation." (PMID 37024472, 2023). "Therefore, we investigated whether homologous Cry2 could be acetylated and whether its acetylation plays a specific role in breast cancer progression." (PMID 37024472, 2023). "Besides this, the down-regulation of CRY2 was present in breast cancer and osteosarcoma." (PMID 35897788, 2022). "In a study investigating the potential significance of Cry2 in breast cancer development, experimenters identified SNPs in the Cry2 gene as potential biomarkers for increased risk of breast cancer, with the variants having a stronger association with non-luminal breast cancers." (PMID 26220712, 2015). "Specifically, aberrant methylation of the circadian genes CLOCK and Cry2 was reported, with shift workers exhibiting CLOCK hypomethylation and Cry2 hypermethylation when compared to day workers, a pattern that has been associated with breast cancer and discussed previously." (PMID 26220712, 2015). "As for CRY2, it can exert an anti-proliferative effect on breast cancer cells because it may bind and inhibit the p65/p50 complex, thus inhibiting the nuclear factor-κB (NF-κB) pathway, but its acetylation in breast cancer impairs this function, the exact mechanism has yet to be studied." (PMID 39139571, 2024). "They report a similar downregulation of PER1, PER2, CRY2, and HLF, in breast cancer samples while CLOCK, ARNTL(BMAL1), and BHLHE40 levels remained relatively unchanged." (PMID 38319971, 2024). "Acetylation of endogenous Cry2 in lysates from MCF7 and T47D breast cancer cell lines, were detected using an anti-acetylated lysine antibody following of Cry2 immunoprecipitation." (PMID 37024472, 2023). "Comparing breast cancer to adjacent tissue, PER1, PER2, PER3, and CRY2 levels are decreased; CLOCK is increased; and CRY1 downregulation was found to escalate directly with breast cancer stage." (PMID 35163264, 2022). "The large majority (10/13) of these genes were reported to play a role in the regulation of estrogen and/or progesterone response in human breast cancer (NCOA7:; NCOA3:; USP22:; MED24:; CCAR1:; CRY2:; STAT5B:; PAGR1:; TAF1:; PHB2:)." (PMID 35996163, 2022). "Low CRY2 and PER1/2 expression is correlated with ER negativity, higher tumor grade and shorter overall survival in breast cancer patients." (PMID 35984550, 2022). "The expression of six rhythm genes, CRY2, NFIL3, PER1, EGR3, NR1D1 and TIMELESS, was significantly changed in breast cancer compared with normal breast tissues." (PMID 35180863, 2022). "For example, a pair of studies showed that all the breast cancer types tested had CLOCK-promoter hypomethylation and Cry2-promoter hypermethylation when compared to controls." (PMID 26220712, 2015). "Breast cancer rates are elevated amongst shift-workers, and breast cancer patients express CLOCK hypomethylation and CRY2 hypermethylation in blood and tumorous breast tissue." (PMID 26252151, 2015).
breast carcinoma (continued). "We silenced CRY2 in breast cancer cell lines (MCF-7) using small-interfering oligos (siRNA) and measured the impact of CRY2 knockdown on a number of cancer-relevant parameters." (PMID 20334671, 2010). "In ER+ breast cancer cells, FOXM1 engages in core circadian gene cryptochrome 2 (CRY2) promoter hypermethylation by forming the FOXM1/DNMT3b (DNA methyltransferase 3b) complex; the FOXM1/DNMT3b complex binds to the CRY2 promoter directly to downregulate the expression of CRY2." (PMID 40003882, 2025). "Moreover, when p300, the Cry2 KAT, was inhibited, the tumor burden of breast cancer was reduced in a murine model." (PMID 37024472, 2023). "Cry2 acetylation by p300 and deacetylation by HDAC6 were identified in breast cancer cells." (PMID 37024472, 2023). "In addition, CRY2 and RORA genes were denoted for the effect on breast cancer though the interaction with other genes or with an environmental factor (NSW)." (PMID 31358835, 2019). "A general observation from this study is a statistically significant diminished expression level of CRY2, and PERs and an increased expression level of CLOCK and TIMELESS in the breast cancer tissue samples in comparison with the adjacent normal tissue samples." (PMID 29958276, 2018). "The results also illustrated that the degree of Cry2 expression can vary between breast cancer types, with the non-luminal breast cancers having higher levels of Cry2 expression when compared to luminal breast cancers." (PMID 26220712, 2015). "For instance, we detected BRCA1 in Breast Cancer, Amyloid Precursor Protein (APP) in Alzheimer’s Disease, INS in A1C measurement and Type 2 Diabetes, PCSK9 in LDL cholesterol levels and SNCAIP in Parkinson’s Disease, and the circadian rhythm gene CRY2 in Morning vs. Evening chronotype." (PMID 32678846, 2020). "Finally, CRY2 knockdown in MCF-7 cancer cells resulted in aberrant regulation of cell differentiation, proliferation, motility, angiogenesis, and apoptosis, thus suggesting a tumour-suppressor role for CRY2 in breast cancer development." (PMID 26220712, 2015).
depression (24 papers, 2010 to 2025). "In this context, altered circadian gene expression -particularly that involving CRY2 - has been linked to depression and sleep disorders, reinforcing the connection between circadian rhythm disruption and mood disturbances." (PMID 41383341, 2025). "Studies have also shown that dysregulation of CRY2 expression can increase susceptibility to depression." (PMID 40487778, 2025). "Relations between CRY2 and depression suggest a positive association between the severity of depression and increased methylation of CRY2 in women affected by overweight/obesity." (PMID 38094940, 2023). "This study suggests that a Cry2 locus is associated with vulnerability for depression, and that mechanisms of action involve dysregulation of Cry2 expression." (PMID 28468274, 2017). "The present results imply that this deficient cry2 expression potentially related to anxiety- and depression-like behavior in HAB mice can be rescued by chronic antidepressant pharmacotherapy." (PMID 26679264, 2016). "In conclusion, the present study provides evidence that deletion of Cry2 is associated with depression-like behavior, namely the sucrose preference test, selectively impinging on the anhedonic endophenotype of depression in the mouse." (PMID 25820768, 2015). "The present study aimed at investigating the direct consequences of Cry2-deficiency on depression-like behavior in the mouse and to determine its molecular signature in the basolateral amygdala." (PMID 25820768, 2015). "Cryptochrome 2 (Cry2) is one of the core components of the molecular circadian machinery which has been linked to depression, both, in patients suffering from the disease and animal models of the disorder." (PMID 25820768, 2015). "The present study firstly assessed the direct consequence of Cry2-deficiency on depression-like behavior and examined its molecular signature in the mouse basolateral amygdala." (PMID 25820768, 2015). "Specifically, they point towards a key role for Cry2, supported by genetic studies in the human population highlighting the association of Cry2 with mood disorders and their depressive episodes." (PMID 25820768, 2015). "With the focus on the cryptochrome genes, earlier studies have indicated CRY1 genetic variants in major depressive disorder and CRY2 genetic variants in seasonal affective disorder, winter depression in particular, and in bipolar type 1 disorder." (PMID 23951166, 2013). "Earlier, CRY2 genetic variants have been associated with winter recurrent depressive disorder, and with the rapid cycling of bipolar type 1 disorder where depressive episodes dominate the clinical course of illness." (PMID 23951166, 2013). "We propose that a CRY2 locus is associated with vulnerability for depression, and that mechanisms of action involve dysregulation of CRY2 expression." (PMID 20195522, 2010). "Our key findings herein are that CRY2 gene variation and expression levels are associated with depression." (PMID 20195522, 2010). "Diurnal profiles of clock genes—alterations of which have been previously reported in both depressed patients and animal models of the disease —and neurotrophic and growth factors implicated in the neurobiological alterations of depression were analyzed in Cry2−/− and Cry2+/+ mice by qRT-PCR." (PMID 25820768, 2015). "Finally, a CRY2 intronic variant, rs10838524, was associated weakly with depression and early morning awakening (P = 0.010, OR = 1.45)." (PMID 20174623, 2010). "To determine whether CRY2 genetic variation is associated with depression, we analyzed circadian clock gene variants in two separate population-based samples, a Swedish sample and a Finnish sample, and report that the CRY2 gene is associated with winter depression." (PMID 20195522, 2010). "Clock gene Arntl, Nr1d1, Per2 and Cry2 expression in the hippocampus was increased in subjects with substance use disorder, while Arntl and Nr1d1 expression was decreased in subjects with major depression." (PMID 37441675, 2023).
depression (continued). "CRY2, a clock gene involved in circadian rhythms, is an interesting hub in the network that upregulates in response to depression, an affective disorder with high comorbidity with anxiety." (PMID 38094940, 2023). "Findings from the targeted examination of clock genes revealed several significant associations with depression (NR1D1 and PER1) and BIP-I (ARNTL, CRY2, RORB) underlining the close relationship with mood disorders." (PMID 36131119, 2022). "Severity of depression was significantly associated with more methylation of clock genes CRY1 (p = 0.034, R2 = 0.16) and CRY2 (p = 0.019, R2 = 0.47)." (PMID 33809270, 2021). "For the assessment of anhedonic behavior, one of the two core symptoms of depression in humans (DSM-V; American Psychiatric Association 2013), Cry2−/− mice and wild-type littermates Cry2+/+ were subjected to the SPT." (PMID 25820768, 2015). "Collectively, these results indicate that Cry2 exerts a critical role in the control of depression-related emotional states and modulates the chronobiological gene expression profile in the mouse amygdala." (PMID 25820768, 2015). "Cry2+/+ and Cry2−/− mice were tested in two standardized paradigms for the assessment of depression-related behavioral despair in rodents, the FST and the TST." (PMID 25820768, 2015). "Of them, NR1D1 genetic variants have been demonstrated to associate with bipolar disorders and depressive disorders, CRY2 (cryptochrome 2) with depressive disorders and bipolar disorders, and CRY1 (cryptochrome 1) with depressive disorders." (PMID 25610405, 2014). "Regarding potential mimetics for affective disorders such as anxiety and depression specifically, literature mining analysis identified links with short-term CR signature gene CRY2 and valproic acid, a histone deacetylase inhibitor utilized for manic episodes of bipolar disorder." (PMID 38094940, 2023). "Additionally, a link between a CRY2 locus and vulnerability to depression has also been demonstrated." (PMID 38094940, 2023). "TEF, CRY1, and CRY2 gene polymorphisms have been associated with depression risk in non-PD individuals." (PMID 37374342, 2023). "Despite this circumstantial evidence for a role of Cry2 in the pathophysiology of mood disorders, a causal link between altered Cry2 expression and depression-like behavior has not been established so far." (PMID 25820768, 2015). "Intact performance of Cry2−/− mice in the FST and the TST supports previous findings and suggests that Cry2 may be specifically relevant for the anhedonic endophenotype of depression." (PMID 25820768, 2015). "Furthermore, mice displaying higher trait-anxiety behavior (HAB) and comorbid depression-like behavior also express lower levels of Cry2 in the hippocampus as compared to normal anxiety/depression-like behavior (NAB) mice." (PMID 25820768, 2015). "It was also of interest that MSET identified circadian rhythm genes including period circadian clock 3 (Per3) and cryptochrome 2 (Cry2) in maternal mPFC with multiple links to depression, as clock genes are emerging as core contributors to depressive pathology in humans and animal models." (PMID 24765068, 2014). "In conclusion, we show data suggesting that variation in CRY2 links to depression." (PMID 20195522, 2010). "Our data indicate that depression in bipolar disorder is related to lowered levels of CRY2 mRNA." (PMID 20195522, 2010). "However, CRY2 and PER2 genetic variants, which might influence the evening and morning signals from the circadian pacemaker system, associate with depression vulnerability in humans." (PMID 21943377, 2011). "These clusters particularly involved genes related to regulatory subunits of cAMP-dependent protein kinases, such as PRKAR2A, cAMP-responsive element-binding pathway, circadian rhythms, such as CLOCK, ARNT1, CRY2, PER1, and PER2, and anxiety and depression, such as NOTCH1, NOTCH2 and ANK2." (PMID 41157308, 2025).
depression (continued). "Concerning PD depression, it has been indicated that TEF rs738499, but not CRY1 rs2287161 or CRY2 rs10838524 gene polymorphisms, were linked to depressive symptoms among PD patients in the Chinese population." (PMID 37374342, 2023). "Indeed, while one study showed that Cry1 or Cry2 single-KO and Cry1/2 double-KO mice showed increased anxiety states, but not depression-like behaviors, another study reported Cry1/2 double-KO displayed increased anhedonia compared to WT mice." (PMID 37441675, 2023). "Our findings revealed that the lack of Cry1 and Cry2 genes (Cry1−/−Cry2−/−) elicits cognitive dysfunction, promotes anxiety-related behavior and results in a decreased sensitivity to cocaine but does not affect depression-like behavior." (PMID 24187535, 2013).
Obesity (17 papers, 2014 to 2024). Accumulation of substantial excess body fat. "In African Americans, the Clock rs1801260 and rs6850524 were negatively associated with the presence of obesity; Bmal1 rs11022775 reduced the risk for dyslipidemia; and the Cry2 rs2292912 increased the risk for dyslipidemia and diabetes." (PMID 34141862, 2021). "Interestingly, a negative regulatory role was demonstrated between CRY2 and obesity as well as an association between mutations in CRY2 and risk of developing obesity." (PMID 38094940, 2023). "CRY1 and CRY2 polymorphisms showed a significant link between diabetes and obesity." (PMID 35053018, 2021). "Additionally, knockout of clock genes, such as aryl hydrocarbon receptor nuclear translocator-like (ARNTL), PERIOD (PER2), and cryptochrome (CRY1/CRY2), increased their susceptibility to obesity and metabolic disorders." (PMID 33424933, 2020). "In the male VLFC group, the minor allele carriers of CLOCK rs9312661, CRY2 rs7951225, and the GG genotype of CRY1 rs11113192 showed increased risks of obesity; however, significances were diminished after the Bonferroni correction." (PMID 35276838, 2022). "Obesity resulted in overall disruption of core clock genes (i.e., Bmal1, Clock, Rev-erbα/Nr1d1, Rev-erbβ/Nr1d2, Per1, Per2, Cry1, Cry2, Dbp and Rorα) in WAT." (PMID 35198059, 2022). "Polymorphisms of human clock genes, such as ARNTL, circadian locomotor output cycles kaput (CLOCK), CRY2, and nuclear receptor subfamily 1, group D, member 1 (NR1D1), have been linked to obesity or some other features of metabolic syndromes." (PMID 33424933, 2020). "Visceral adipocytes isolated from women with obesity showed that during 24 h, Bmal1 expression changes in the first 12 h in visceral adipocytes compared with lean women, while Rev-reb and Cry2 expression is up-regulated during the 24 h in visceral and subcutaneous adipocytes." (PMID 39083072, 2024). "Interestingly, Per1, Per2, and Cry2 expression is unchanged in obesity but alters in pregnant obese rats." (PMID 39083072, 2024). "In the present study, conducted in a population of subjects with overweight/obesity, we observed an association between PM exposure measured in the week before the blood drawing and the methylation of circadian cycle genes (i.e., CLOCK, CRY1, CRY2, PER1, PER2, and PER3)." (PMID 33513987, 2021). "CRY2 expression was related to age, DBP expression was related to age, tumor type, smoking history, and RORA expression was related to TNM stage, obesity index, and tumor type in KIRP patients (p < 0.05)." (PMID 34977153, 2021). "The present study aimed to evaluate the effects of PM2.5 and PM10 on the methylation profile of the clock genes ARNTL, CLOCK, CRY1, CRY2, PER1, PER2, and PER3 in a population of 200 women with obesity." (PMID 33513987, 2021). "We identified CRY2 and REV-ERB ALPHA as the clock genes upregulated in obesity during the 24 h period." (PMID 25365257, 2014). "We identified CRY2 and REV-ERB ALPHA as the clock genes upregulated in obesity during the 24 h period and that REV-ERB ALPHA is an important gene associated with MS." (PMID 25365257, 2014). "The 24 h pattern of clock genes showed that obesity alters the expression of CLOCK, BMAL1, PER1, CRY2 and REV-ERB ALPHA in adipocytes with changes found in CRY2 and REV-ERB ALPHA throughout the 24 h period." (PMID 25365257, 2014). "Utilizing Cry1−/− and Cry2−/− mice, we demonstrate for the first time that Cry1−/− loss interferes with HFD-induced obesity, and that the physiological basis of this effect is not related to reduced energy intake." (PMID 24782829, 2014). "To confirm whether CRY2 and REV-ERB ALPHA are altered in human obesity, we next measured the mRNA expression of clock genes in VAT and stromal cells from lean and obese subjects." (PMID 25365257, 2014). "In this study, we demonstrate that ablation of Cry1, but not Cry2, prevents high-fat diet (HFD)-induced obesity in mice." (PMID 24782829, 2014).
Obesity (continued). "In a time-course experiment with white adipose tissue biopsies from people with healthy weight or obesity or T2D, no variation in the rhythm and amplitude of core-clock (PER1, PER2, PER3, DBP, BMAL1, and CRY2), metabolic (PGC1), and clock-related (REVERB) genes could be observed in biopsy tissues." (PMID 37475884, 2023).